WNT5A (Wnt family member 5A)
Diseases named in the same sentence as WNT5A in open-access papers (continued):
Sharing a sentence is not in itself a finding about the gene and the disease.
Stroke (6 papers, 2012 to 2023). Sudden impairment of blood flow to a part of the brain due to occlusion or rupture of an artery to the brain. "This was an early event considering that at 3–7 days after stroke, the levels of Wnt5a in blood decreased." (PMID 35622188, 2023). "Limiting the Wnt5a activity via Box5 reduces stroke size, suggesting neuroprotection pertinent to onset and progression of retinal degenerations and stroke consequences." (PMID 35622188, 2023). "We provide evidence that Wnt5a is upregulated in stroke penumbra and augmented in the bloodstream, favoring activation of immune cells and their recruitment into damaged brain areas." (PMID 35622188, 2023). "DHA-decreased Wnt5a expression is concurrent with a drop in NFkB-driven inflammatory cytokine expression, revealing mechanisms after stroke, as in RPE cells exposed to UOS." (PMID 35622188, 2023). "As macrophage infiltration occurs during stroke, the increase in Wnt5a more than likely enhances the destructive activity of these cells in the brain." (PMID 35622188, 2023). "In the patient that suffered a perioperative stroke and died on postoperative day 20, we observed an increase of WNT-5a until 8 h after surgery and a return to the baseline value at 48 h." (PMID 36440011, 2022). "To test whether IR increases Wnt5a secretion and signaling, we induced stroke in rats by middle cerebral artery occlusion (MCAo) for 2 h and, 1 h later, injected IV saline (vehicle) or DHA." (PMID 35622188, 2023). "DHA treatment brought down bloodstream Wnt5a protein after 24 h of stroke onset." (PMID 35622188, 2023). "Furthermore, we assessed Wnt5a mRNA in A1 penumbra, A3 stroke core, and as control A2 and A4 that correspond to contralateral parts of A1 and A3." (PMID 35622188, 2023). "The kinetic profile of WNT-5a in this patient may be the result of an additional inflammatory response to the stroke that occurred perioperatively." (PMID 36440011, 2022). "In perspective, Prrx2 or Wnt5a inhibitor maybe a new drug to treat ischaemia‐related cardiovascular diseases, such as acute MI and stroke." (PMID 31880857, 2020). "Consequently, WNT-5A emerges as an important means of astrocyte-microglia communication and we, therefore, suggest WNT-5A as a new player in neuroinflammatory conditions, such as neurodegenerative disease, hypoxia, stroke, injury and infection." (PMID 22647544, 2012). "The signaling pathways involved in RPE cell damage and in stroke display similarities in the stroke penumbra, Wnt5a synthesis increases in the ipsilateral side, Wnt5a protein elevation in both sides and presence in the blood plasma after stroke, providing a potential stroke biomarker candidate." (PMID 35622188, 2023). "Post-stroke, we observed a similar trend seen in the RPE: Wnt5a transcription was elevated at 1 and 3 days after stroke only in penumbra at the ipsilateral hemisphere, while the expression in the contralateral side was not affected." (PMID 35622188, 2023).
chronic kidney disease (5 papers, 2019 to 2024). Impairment of the renal function secondary to chronic kidney damage persisting for three or more months. "In this study, we observed that serum Wnt5a concentration was higher in the advanced stages of chronic kidney disease, particularly during stage 3." (PMID 32491086, 2020). "This study evaluated whether Wnt5a levels influence recovery and transition to acute and chronic kidney disease after AKI." (PMID 38913943, 2024). "However, it was observed that the Wnt5a concentrations were statistically significantly higher in the more advanced stages than in the earlier stages of chronic renal disease (stages 3 and 4 versus stages 1 and 2)." (PMID 32491086, 2020). "However, there is a need to carry out complementary studies in order to demonstrate the participation of Sfrp5 and Wnt5a within the pathophysiology of chronic kidney disease." (PMID 32491086, 2020). "This phenomenon suggests that Sfrp5 and Wnt5a might be involved in development and evolution towards end-stage renal disease." (PMID 32491086, 2020). "In addition, in a severe ARPKD sub-group where patients reached end stage renal disease at an age of 5 years or younger, there was a 2.7-fold increase in WNT5A mRNA expression (n = 6, p < 0.05)." (PMID 30414501, 2019). "However, growing evidence suggests that YAP and Wnt5a might functionally interact in cancer and chronic kidney disease." (PMID 33643710, 2021). "However, no studies on the participation of Sfrp5 and Wnt5a in patients with chronic kidney disease have been conducted." (PMID 32491086, 2020). "WNT5A, a typical glycoprotein of the non-canonical pathway, has been verified to have pro-inflammatory functions in urosepsis, nephrogenic diabetes insipidus (NDI), and chronic kidney disease (CKD)." (PMID 33790866, 2021).
diabetic nephropathy (5 papers, 2019 to 2025). "However, the association of Wnt5a–Ca2+ and mitochondrial dysfunction in diabetic nephropathy (DN) progression remains unknown." (PMID 40008536, 2025). "However, the association between Wnt5a, T2DM patients and diabetic kidney disease (DKD) is unknown." (PMID 31890678, 2019). "In the current study, we combined human, mouse, and cellular studies to provide evidence that CD146 directly binds to Wnt5a, activates noncanonical Wnt signaling, and promotes subsequent inflammatory responses in diabetic nephropathy." (PMID 33462195, 2021). "Taken together, our findings suggest that by directly binding to CD146, Wnt5a-induced noncanonical signaling is a contributing mechanism for renal tubular inflammation in diabetic nephropathy." (PMID 33462195, 2021). "Taken together, our studies suggest that through binding to CD146, Wnt5a-induced noncanonical signaling is a contributing mechanism for renal tubular inflammation in diabetic nephropathy." (PMID 33462195, 2021).
emphysema (5 papers, 2017 to 2022). "β-catenin dependent Wnt signaling improved regeneration and survival in a model of emphysema, and inhibition of WNT5A, and thus presumably some component of β-catenin independent Wnt signaling, improved repair in a model of COPD." (PMID 35559731, 2022). "Similar to what is seen in Wnt5A and emphysema, an exposure of CS to PMBC cells of COPD patients was found to induce Wnt5B expression, along with an increased expression of genes related to small airway remodeling, such as fibronectin, matrix MMP-2, MMP-9, and Snail." (PMID 28588349, 2017). "In this context, an overexpression of mature lung-specific Wnt5A was found to functionally attenuate canonical Wnt-driven alveolar epithelial cell wound healing and transdifferentiation in vitro, which in turn exacerbate airspace enlargement in elastase- or CS-induced experimental emphysema in vivo." (PMID 28588349, 2017). "It is also notable that several independent datasets from emphysema patients, in which repair capacity is diminished, show significant downregulation of VANGL2 and WNT5A." (PMID 33195213, 2020). "For instance, an overactivation of the non-canonical WNT signal, mostly represented by a WNT5A overexpression, has been reported in alveolar epithelial cells from COPD patients, and inhibition of WNT5A results in attenuation and amelioration of elastase-induced emphysema in mice." (PMID 35742983, 2022).
Hyperglycemia (5 papers, 2015 to 2026). An increased concentration of glucose in the blood. "In the current study, it was assumed that MZF1 associates with SETD8 to regulate WNT5A transcription, thus resulting in hyperglycemia-induced glomerular endothelial inflammation in DN." (PMID 35350980, 2022). "Collectively, impaired pancreatic insulin secretion by aberrant Wnt5a/β-catenin activation may underlie the hyperglycemia associated with PDAC." (PMID 41593307, 2026). "Our data may suggest that inhibiting expression of WNT5A in glomerular endothelial cells can reduce renal injury caused by hyperglycemia." (PMID 35350980, 2022). "Plasma Wnt5a and pancreatic islet β-catenin levels were higher in patients with PDAC and correlated with the degree of hyperglycemia and insulin deficiency." (PMID 41593307, 2026). "MZF1 links with SETD8 to regulate WNT5A expression in HGECs, thus elevating levels of hyperglycemia-mediated inflammatory factors in glomerular endothelium of DN patients and rats." (PMID 35350980, 2022). "Hyperglycaemia affects the activity of important signalling pathways that are crucial for mouse embryogenesis, including the hypoxia (Hif1α), PDGFRa, Wnt-β-catenin (GSK3β, β-catenin) and the Wnt-planar cell polarity (PCP) (Vangl2, Daam1, Wnt5a, etc.)pathways." (PMID 25540130, 2015). "Maternal hyperglycaemia is known to affect the expression of components of the Wnt-PCP pathways, including Wnt5a, Vangl2, Rock1 and Daam1 in mouse embryos, suggesting that abnormal Wnt-PCP signalling might underlie diabetic embryopathies." (PMID 25540130, 2015).
invasive breast carcinoma (5 papers, 2013 to 2018). A carcinoma that infiltrates the breast parenchyma. "Previous studies have shown that loss of WNT5A is associated with early relapse of invasive breast cancer and, in a retrospective study, immunohistochemical detection of WNT5A in tumors was inversely correlated with metastasis and survival." (PMID 23484019, 2013). "In primary invasive breast cancer tissue, we previously reported that low expression of WNT‐5A protein is associated with a higher histological grade of tumors and earlier disease recurrence in patients, reflecting a more rapid development of distant metastases." (PMID 23727359, 2013). "The relationship between Wnt5a expression and clinicopathologic factors was assessed in invasive breast cancer (n = 178) resected at Hiroshima University Hospital between January 2011 and February 2014." (PMID 29765514, 2018). "Serial sections of pathological specimens of invasive breast cancer revealed that Wnt5a was expressed in the cytoplasm, whereas ALCAM was expressed in the plasma membrane." (PMID 29765514, 2018). "Wnt5a was expressed in 69 of 178 cases (39%) of invasive breast cancer and correlated strongly with estrogen receptor (ER) expression (P < 0.001)." (PMID 29765514, 2018). "Several previous studies have addressed the effects of WNT5A on the progression of invasive breast cancer." (PMID 23484019, 2013). "Of the 178 cases of invasive breast cancer, 69 (39%) were Wnt5a-positive and 109 (61%) were Wnt5a-negative." (PMID 29765514, 2018). "In addition, the tumor tissue was Wnt5a negative in 10 cases of the 17 ductal invasive breast cancer patients." (PMID 24944588, 2014).
invasive ductal carcinoma (5 papers, 2011 to 2023). "The loss of WNT5A is associated with early relapse in invasive ductal breast carcinomas (IDC) and short recurrence-free survival." (PMID 24586797, 2014). "The first immunohistochemical study on WNT5A was performed on 96 patients with primary invasive ductal carcinoma (IDCs) using a specific anti-WNT5A antibody." (PMID 30171384, 2018).
myeloid leukemia (5 papers, 2014 to 2018). A clonal proliferation of myeloid cells and their precursors in the bone marrow, peripheral blood, and spleen. "Mice hemizygous for Wnt5a develop clonal myeloid leukemias and B cell lymphomas and display loss of Wnt5a function in tumor tissues." (PMID 26056595, 2014). "Wnt5a hemizygous mice developed myeloid leukemia and B-cell lymphoma, that are common in clonal origin, and exhibited a loss of Wnt5a function in tumor tissues." (PMID 24944588, 2014). "The only exception to this, is myeloid leukemia, in which Wnt-5a is downregulated and functions as a tumor suppressor." (PMID 26895946, 2016). "Wnt5a and its receptor ROR2 act synergistically to increase autocrine signaling and inhibits canonical Wnt signaling in myeloid leukemia cells." (PMID 29213214, 2017).
skin cancer (5 papers, 2012 to 2019). "Wnt5a is of major importance in maintaining the tumor phenotype in human SCCs, implying that Wnt5a serves as an oncogenic driver in skin cancer." (PMID 31438551, 2019).
viral infections (5 papers, 2017 to 2025). "While direct evidence linking WNT5A to viral infection is scarce, the Wnt pathway is generally recognized as a critical modulator of replication for diverse viruses, including human coronaviruses and herpesviruses." (PMID 41328592, 2025). "The effect of Wnt5a or control buffer treatment on the WRK reporter line without virus infection is shown as a reference." (PMID 28885975, 2017). "Finally, signaling molecules such as WNT5A, MET, and NETO2 are modulated by bacterial and viral infections (including SARS-CoV-2 and M. tuberculosis) to alter cell survival, inflammation, and proliferation pathways, reinforcing the pathogenic role of these exosome-borne receptors." (PMID 41440381, 2025). "Notably, WNT5A, SELENON, and SLC16A13 exerted similar enhancing effects on both the single-stranded negative-sense RNA virus BPIV-3c and the single-stranded positive-sense RNA virus BEV, highlighting their broad and critical roles in facilitating viral infection." (PMID 41328592, 2025).
adenoma (4 papers, 2011 to 2024). A neoplasm arising from the epithelium. "Thus, WNT5A expression is elevated in CCs compared to normal colon and during the progression from adenoma to carcinoma." (PMID 22073312, 2011). "Four DEGs (MMP-7, MYC, WNT-5A, and AXIN2) were upregulated in tumor vs. normal tissues, or adenoma vs. normal tissue in TCGA, which was overlapped with our data." (PMID 32258125, 2020).
B-cell lymphoma (4 papers, 2013 to 2017). "However, in hematological malignancies, including B-cell lymphoma, WNT5A acts as a tumor suppressor able to antagonize the WNT/β-catenin signaling and it is found silenced by tumor-specific methylation." (PMID 28912427, 2017).
Cirrhosis (4 papers, 2009 to 2023). A chronic disorder of the liver in which liver tissue becomes scarred and is partially replaced by regenerative nodules and fibrotic tissue resulting in loss of liver function. "Therefore, our work was designed to figure out impacts of lncRNA SNHG1 on cirrhosis by orchestrating HLC differentiation of BMSCs via miR-15a/SMURF1/UVRAG/ATG5/Wnt5a axis." (PMID 35194023, 2022). "Conclusively, lncRNA SNHG1 silencing might facilitate HLC differentiation from mouse BMSCs and alleviate cirrhosis via the miR-15a/SMURF1/UVRAG/ATG5/Wnt5a axis." (PMID 35194023, 2022). "Increased levels of Wnt5a transcripts were detected in chronic hepatitis, cirrhosis and HCC." (PMID 19849855, 2009). "However, immunostaining of Wnt5a protein showed a bell-shaped pattern: low to undetectable levels were present in normal tissue and in tumor samples, whereas strong immunostaining was seen in chronic hepatitis, cirrhosis and dysplastic liver cells." (PMID 19849855, 2009). "Second, to explore the extensive role of Wnt5a in progression of chronic HBV infection, we should consider other HBV-infected diseases, including cirrhosis and HCC." (PMID 38062395, 2023). "LncRNA SNHG1 or SMURF1 silencing or miR-15a overexpression promoted differentiation of BMSCs into HLCs and repressed cirrhosis of mice by upregulating ATG5 and Wnt5a via UVRAG." (PMID 35194023, 2022). "Another critical finding in our study was that overexpressed UVRAG promoted ATG5/Wnt5a activation to decrease HLC differentiation of BMSCs, thus alleviating cirrhosis." (PMID 35194023, 2022). "Compared to normal tissue, Wnt5a mRNA expression was strongly induced in HCC, as well as in chronic hepatitis and cirrhosis." (PMID 19849855, 2009). "Further, we testified the findings in the cirrhosis mouse model and obtained similar results as in vitro experiments: injection of SMURF1 overexpression HGF-induced BMSCs aggravated the degree of cirrhosis in mice, which was abolished by oe-UVRAG, rapamycin, or recombinant Wnt5a." (PMID 35194023, 2022).
craniorachischisis (4 papers, 2010 to 2024). Craniorachischisis is the most severe form of neural tube defect in which both the brain and spinal cord remain open to varying degrees. "Ltap/Vangl2 and Wnt5a may interact genetically to increase NTD penetrance; as a result, mice carrying LtapLp/+ and Wnt5a−/− mutations displayed craniorachischisis." (PMID 38804432, 2024). "All Wnt5a-/-;LtapLp/+ mutants exhibited craniorachischisis, indicating a drastic increase in penetrance as compared to the craniorachischisis phenotype displayed by Wnt5a-/- (1 in 34) or LtapLp/+ animals (0 in more than 100)." (PMID 21864354, 2011). "Disruption of Wnt5a can also lead to craniorachischisis, and Wnt5a genetically interacts with Vangl2 mutants." (PMID 20704721, 2010). "However, Wnt5a−/−;Vangl2+/Lp embryos exhibit craniorachischisis with a penetrance of 100%, implicating Wnt5a in PCP regulation." (PMID 25596276, 2015). "Genetic interaction between Wnt5a and Ltap/Vangl2 could enhance the penetrance of neural tube closure and all Wnt5a-/-; LtapLp/+ mice exhibited craniorachischisis." (PMID 21864354, 2011).
cutaneous squamous cell carcinoma (4 papers, 2012 to 2025). "Alterations in Wnt signaling have also been observed in cutaneous squamous cell carcinoma with which PeSCC is most analogous; these include upregulation of WNT5A and FZD6 and raised levels of β-catenin." (PMID 40486660, 2025).
cyst (4 papers, 2006 to 2023). A sac-like closed membranous structure that may be empty or contain fluid or amorphous material. "Wnt5a has been implicated in the formation of tubular lymphatic vessels by regulating the WNT/PCP pathway, since cyst-like lymphatics are detected in the skin of Wnt5a-deficient mice." (PMID 36895637, 2023). "Besides, Notch1 can activate the Wnt5a promoter by RBP-Jκ, suggesting that Wnt5a is a primary target gene of the activated RBP-Jk to control normal hair follicle development or cyst formation." (PMID 33511139, 2020).
gastric adenocarcinoma (4 papers, 2019 to 2025). "Similarly, Wnt5a gene expression has been associated with better overall survival in lung squamous cell carcinoma, but with a poor prognosis in gastric adenocarcinoma." (PMID 41008809, 2025). "Wnt5a expression in CAFs (Wnt5aCAF) was significantly lower than Wnt5a in gastric adenocarcinoma (P<0.05)." (PMID 33854601, 2021). "Public datasets validated WNT5A expression in lung squamous cell carcinoma (LUSC) and stomach adenocarcinoma (STAD) samples." (PMID 39176352, 2024). "Based on the IHC score of Wnt5a and CXCL12 expression in the GC area and adjacent fibroblast area, CXCL12CAF expression was significantly higher than CXCL12 in gastric adenocarcinoma (P<0.001)." (PMID 33854601, 2021).
Glucose intolerance (4 papers, 2020 to 2024). Glucose intolerance (GI) can be defined as dysglycemia that comprises both prediabetes and diabetes. "Maternal inulin treatment improved glucose intolerance by changing DNA methylation and gene expression of Wnt5a and Pi3k in mice exposed to a maternal HF diet." (PMID 32116778, 2020). "Additionally, enlarged adipocytes in the obese state have shown increased secretion of Wnt5a that could impede insulin signaling and develop glucose intolerance by activating the non-canonical Wnt5a/PCP pathway." (PMID 39692821, 2024).
ischemia (4 papers, 2023 to 2025). A hypoperfusion of the BLOOD through an organ or tissue caused by a PATHOLOGIC CONSTRICTION or obstruction of its BLOOD VESSELS, or an absence of BLOOD CIRCULATION. "Mechanistic studies have demonstrated that SFRP5 can inhibit myocardial inflammation and injury following a mouse model of ischemia/reperfusion injury, possibly exerting anti-inflammatory action via inhibition of Wnt5a." (PMID 37504530, 2023). "When MI happens, due to ischemia, Prrx1 is activated by TGF-β through S-nitrosylation to enhance Wnt5a signaling, which induces FMD." (PMID 41168006, 2025).